HOXA10 (homeobox A10)
Diseases named in the same sentence as HOXA10 in open-access papers (continued):
Sharing a sentence is not in itself a finding about the gene and the disease.
endometriosis (continued). "Combining this observation with the fact that in patients with endometriosis there is a decrease in HOXA10 expression, at least in part responsible of the insufficient uterine receptivity of endometriosis patients, makes HOXA10 a potential target of aberrant methylation in endometriosis." (PMID 30309386, 2018). "However, as discussed in advance, the data presented are in accordance with recent genome‐wide methylation study of the HOXA10 gene in endometriosis patients." (PMID 30309386, 2018). "Hoxa10 expression is notably highly conserved in the female reproductive tract of both mice and humans, making this gene a potential target in animal modeling of endometriosis development." (PMID 28716123, 2017). "Authors suggested that impaired decidualization and dysfunctional expression of genes related to Müllerian embryogenesis (like the downstream targets of HOXA10) could be critical to the development of endometriosis." (PMID 26759613, 2016). "Women with endometriosis display aberrant expression of genes in their eutopic endometrium, many of which (including HOXA10, aromatase, progesterone receptors, matrix metalloproteinases, and ab-integrin) have been implicated in endometrial development and receptivity." (PMID 26089099, 2015). "Transfection of ESCs with miR-135a/b or miR-135a/b inhibitors resulted in altered expression of HOXA10 mRNA and protein and this may suppress endometrial receptivity in endometriosis." (PMID 24927773, 2014). "The decreased expression of HOXA10 may designate impaired endometrial receptivity in patients with endometriosis." (PMID 24639744, 2013). "Additionally, DNA hypermethylation and suppressed expression of HOXA10 have been shown in the endometrium of women with endometriosis." (PMID 22608095, 2012). "Thus, the HOXA10 DNA methylation could be a potential additional biomarker for the diagnosis and prognosis of endometriosis." (PMID 36979165, 2023). "Therefore, in endometriosis, the downregulation of HOXA10 through DNA methylation could alter the uterine environment, such as reducing the number of pinopods in the eutopic endometrium." (PMID 36979165, 2023). "Thus, the low expression of HOXA10 in endometriosis women could inhibit cell differentiation in eutopic endometrium during the secretory phase." (PMID 36979165, 2023). "The suppression of the HOXA10 gene, which naturally modulates the action of progesterone, may additionally favor progesterone resistance and contribute to impaired implantation in women with endometriosis." (PMID 35409163, 2022). "Since the report, published over a decade ago, of HOXA10 hypermethylation in eutopic endometrium from women with endometriosis, which ventured the view that “endometriosis may also be an epigenetic disease”, accumulating evidence provides strong support for this view." (PMID 27062244, 2016). "This study aimed to evaluate compartment-specific immunohistochemical expression patterns of HOXA-10, HOXA-11, CD44, β1 integrin, ECM-1, and focal adhesion kinase (FAK) in women with endometriosis-related implantation failure." (PMID 42010698, 2026). "Downstream progesterone-responsive genes, such as HOXA10, IGFBP1, and FOXO1, are also affected by DNA methylation and histone modifications, and are altered in endometriosis." (PMID 41009686, 2025). "In contrast, patients with endometriosis have dysregulated UF-EV profiles marked by reduced miR-200b-3p and increased miR-145-5p levels, resulting in the inhibition of NOTCH1 and HOXA10, two genes essential for trophoblast invasion and decidualisation." (PMID 41296460, 2025). "Immunomodulation therapy alters the expression of HOXA10 and HOXA11, which would improve the implantation microenvironment in endometriosis and other inflammatory diseases that interfere with the proper regulation of the HOXA10 and HOXA11 genes." (PMID 40305321, 2025).
endometriosis (continued). "Several genes exhibit aberrant expression in endometriosis, including CYP19A1, which is involved in the synthesis of estrogen, and Hoxa10/HOXA10, which is crucial for endometrial receptivity." (PMID 41415877, 2025). "Homeobox A10 (HOXA10) and/or leukaemia inhibitory factor (LIF)—targets of 12 miRNAs—were decreased in eutopic endometrium of women with endometriosis-related infertility compared to controls." (PMID 37877421, 2023). "Endometrial expression of Hoxa10, Hoxa11, Igfbp1, Klf9 (Kruppel-like factor 9) and PGR was reduced in mice when endometriosis was induced in the peritoneal cavity (proximal) compared to control eutopic endometrium." (PMID 36830705, 2023). "Taken together, in the endometrium resected from rats with endometriosis, metformin increased LIF protein and mRNA expression, and enhanced HOXA10 protein expression dependent on metformin dosage." (PMID 35273494, 2022). "Other critical PGR signaling mediators: WNT4, HOXA10, MIG6, FOXO1, and CRISPLD2 decrease in the eutopic endometrium with endometriosis, especially during the secretory phase." (PMID 35203298, 2022). "This study also revealed that improvement in endometrial receptivity in rats with endometriosis treated with metformin also correlated with an increase in the expression of the implantation markers, LIF and HOXA10, within the endometrium." (PMID 35273494, 2022). "IGFBP-1 is downregulated in endometriosis via reduced levels of forkhead box O1 (FOXO1) and homeobox A10 (HOXA10), upstream target genes of IGFBP-1." (PMID 24179489, 2013). "In particular, the role of transcription factors HOXA10 and HOXA11 and their downstream genes in endometriosis and related infertility has been shown." (PMID 22952593, 2012). "Women with endometriosis exhibit significantly lower levels of HOXA10 gene expression than women without the condition; this pattern is seen in various populations." (PMID 40305321, 2025). "Additionally, melatonin has been shown to increase the expression of genes like LIF, HOXA10, and HOXA11 in endometriosis mice." (PMID 39409719, 2024). "More precisely, HOXA-10 gene expression was 3.5-fold downregulated in women with endometriosis-related infertility compared to those without endometriosis." (PMID 38813329, 2024). "The homeobox A10 (HOXA10) gene is known to be related to endometriosis; however, due to a lack of knowledge/evidence in the pathogenesis of endometriosis, the mechanisms that link HOXA10 to endometriosis still need to be clarified." (PMID 37629050, 2023). "Currently, sufficient data are provided to support the observation of low levels of HOXA10 expression in women with endometriosis compared to women without endometriosis." (PMID 37629050, 2023). "Patients with endometriosis do not show the normal physiologic rise in HOXA10 and HOXA11 during the mid-luteal phase of the menstrual cycle." (PMID 36387918, 2022). "A number of implantation markers such as αvβ3 integrin, LIF, homeobox A10 (HOXA10) and HOXA11 are aberrantly expressed in patients with endometriosis and may contribute to infertility in some women with endometriosis." (PMID 34149619, 2021). "We want to pay special attention to the relation of impaired expression of HOXA10 and HOXA11 to endometriosis since this disease involves the ability of the endometrial stroma to self-organize ectopically, i.e., to “ignore” conditions of an ectopic environment." (PMID 32850789, 2020). "Of interest, studies reported that HOXA10 levels were not increased in women affected by endometriosis leading to infertility." (PMID 31717614, 2019). "Based on our findings, we propose that two molecular mechanisms are involved in endometriosis pathogenesis, where, firstly, HOXA9 and HOXA10 genes are regulated by miR-139-5p among other factors and are potentially involved in endometriosis-associated infertility." (PMID 30487429, 2018).
endometriosis (continued). "During the last decade, several studies have reported abnormal methylation patterns of selected genes, e.g. steroidogenic factor 1, progesterone receptor B, oestrogen receptor-β, HOXA10, HOXA11, COX-2 and aromatase, in endometriotic lesions and endometria of endometriosis patients." (PMID 26759613, 2016). "HOXA10 and HOXA11 are known to be differentially methylated in endometriosis." (PMID 24603652, 2014). "Moreover, this study suggests that patients with endometriosis and infertility have lower levels of endometrial HOXA-10 gene expression than those without fertility disorders." (PMID 38813329, 2024). "Thus, indicating that the variations in geography and population are not the confounding factors for HOXA10 DNA methylation in endometriosis patients." (PMID 36979165, 2023). "Therefore, HOXA10/Hoxa10 will be at its highest during the mid-to-late secretory phase of the menstrual cycle in healthy fertile women but not in women with endometriosis, which is believed to influence one’s fertility." (PMID 37629050, 2023). "Thus, the aims of this study were to first to examine VEGF and MMP-9 expression from endometriotic implants in rats with endometriosis and second to investigate the effects of metformin on endometrial receptivity through regulation of LIF and HOXA10 expression." (PMID 35273494, 2022). "Furthermore, non-human primates induced with endometriosis exhibit reduced HOXA10 and αv/β3 integrin expression." (PMID 31387263, 2019). "In line with the hypothesis of a pathogenetic mechanism for endometriosis that occurs at an embryonic level, in this study we preferred to analyze the methylation status of the HOXA10 gene in the peripheral blood and not in the endometrial tissue." (PMID 30309386, 2018). "The involvement of this miRNA in endometriosis had previously not been determined; however, decreased expression of miR-139-5p occurred in endometrial cancer tissues where its levels are inversely correlated with HOXA10 expression." (PMID 30487429, 2018). "Endometriosis has been recognized as a disease accompanied by aberrant methylation and expression of steroidogenic factor-1 (SF-1), estrogen receptor 2 (ESR2), progesterone receptor (PR-B) and HOXA10 genes in the eutopic endometrium of women with endometriosis." (PMID 22233680, 2012). "Hence, just as endometrial hyperinnervation, or downregulation of PGR, or HOXA10 promoter hypermethylation, CAM-carrying endometria are not exclusively found in women with endometriosis, these aberrations are not sufficient to inevitably cause endometriosis exclusively." (PMID 36830705, 2023). "Therefore, this systematic review aims to examine studies on the differential expression of HOXA10 in women with and without endometriosis and the relationship between the HOXA10 gene and endometriosis, which may interrupt fertility across the population." (PMID 37629050, 2023). "During a normal implantation process, endometrial epithelial expression of homeobox A10 (HOXA10) and HOXA11 increases in the luteal phase, but this fails to occur in endometriosis because of dysregulated promoter methylation." (PMID 30104541, 2018). "The expression of HOXA10 and HOXA11 genes were decreased during the secretory phase of endometrium in some nonoptimal conditions such as in adenomyosis, endometriosis, myoma idiopatic infertility." (PMID 24639724, 2013). "This increase in HOXA10 and HOXA11 levels is not observed in patients with endometriosis." (PMID 33411206, 2021). "In addition to regulating αv/β3 integrin, HOXA10 regulates FKBP52, a PGR regulator required for implantation and decidualization and reduced in the endometrium of women and non-human primates with endometriosis." (PMID 31387263, 2019).
Infertility (48 papers, 2012 to 2025). "This review aims to investigate the molecular interactions between benign reproductive system disorders, infertility, and the involvement of HOXA10/A11 genes in their development and associated pathophysiology." (PMID 40305321, 2025). "In contrast, miR-21 loss in eutopic glands is linked to impaired decidualization (HOXA10/IL-15 axis), with downstream infertility implications." (PMID 41226749, 2025). "Infertility and implantation failure are associated with this inflammation and decreased expression of HOXA10 and HOXA11." (PMID 40305321, 2025). "Dysregulation of HOXA10 has been associated with infertility, recurrent pregnancy loss, and poor outcomes in assisted reproductive technologies (ART)." (PMID 39915377, 2025). "It is likely that the downregulation of the Hoxa10 gene promoter, which probably increases preimplantation loss and infertility in females, is due to an increase in DNA methylation level." (PMID 36551846, 2022). "HOXA-10 gene expression was decreased in the endometrium of infertile women which is likely caused by the increased miRNA 135b expression." (PMID 32685419, 2020). "Based on our results, the increase in the levels of miRNA-135b had caused the decrease in HOXA10 mRNA expression in endometrial cells of the infertile women." (PMID 32685419, 2020). "The HOXA10 gene may regulate cholesterol synthesis in endometrial stromal cells, and its downregulation can lead to infertility associated with endometrial disorders." (PMID 40509092, 2025). "These reproductive diseases and PCOS are associated with infertility partly by an endometrial dysfunction that, in turn, may be explained by the increased DNA methylation at the HOXA10 promoter." (PMID 37047828, 2023). "Infertility due to implantation failure was noted in female mice with HOXA-10 mutation." (PMID 35292717, 2022). "HOXA10 may be involved in endometrial development and uterine receptivity for blastocysts because HOXA10-deficient mice display infertility due to implantation and decidualization failure." (PMID 34638846, 2021). "Therefore, we hypothesized that the aberrant CAPN7 expression in the eutopic endometrium of the infertile women with ENDO may cause failure of embryo implantation via degradation of HOXA10." (PMID 29459744, 2018). "Although HOXA10 and the prokineticin gene family are known to be involved in infertility, the exact mechanisms by which these genes influence fertility are not fully understood." (PMID 39915377, 2025). "There is every reason to believe that abnormal promoter hypermethylation of the HOXA10 and HOXA11 genes causes their functional shutdown, which in turn leads to disruption of the implantation process and eventually to infertility." (PMID 41153447, 2025). "The study aimed to assess potential differences in the expression levels of infertility-related genes (HOXA10 and the prokineticin gene family) between the endometrial tissue of healthy controls and patients diagnosed with endometrial polyps or myoma uteri." (PMID 39915377, 2025). "PDX protein and HOXA10 mRNA expression in mid-luteal phase endometrial tissue samples of RIF patients were compared with those of unexplained infertile and fertile controls." (PMID 39795629, 2025). "Other miRNAs, like as miR-27a-3p, target HOXA10 and are more prevalent in infertile women, emphasizing the sensitivity of this developmental pathway to miRNA-mediated regulation." (PMID 40427016, 2025). "Compared to women with DE or OE, those with SE have lower antral follicle counts, longer infertility durations, and more alterations in HOXA10 expression." (PMID 40305321, 2025). "Although the roles of the HOXA10 gene and prokineticin gene family in infertility are well-recognized, the precise mechanisms by which these genes influence fertility remain poorly understood." (PMID 39915377, 2025).
Infertility (continued). "There was asignificant difference between the groups, with infertile women with endometritishaving lower HOXA10 expression values than the women in the controlgroup (fertile without endometritis)." (PMID 38801313, 2024). "Based on the HScore analysis by immunohistochemistry, it was possible to observe areduction in the expression of HOXA10 and HOXA11in infertile women compared to women in the control group (fertile withoutendometritis)." (PMID 38801313, 2024). "This hypermethylation occurs specifically in the promoter region of the HOXA10 gene, resulting in its reduced expression, negatively impacting the endometrial environment and contributing to infertility." (PMID 39311136, 2024). "Miss-expression of HOXA10 has been reported to contribute to infertility and mice with deletion of Hoxa10 have severe defects in decidualisation and implantation." (PMID 35514537, 2022). "Accordingly, the goal of this study was to substantiate the interdependent expression of micro-RNA 135b and HOXA-10 in the endometrium during the implantation window of infertile women." (PMID 32685419, 2020). "Significant negative correlation was observed between the expression of miRNA 135b and HOXA-10 mRNA in infertile women (p=0.021; r=−0.607)." (PMID 32685419, 2020). "The expression of miRNA 135b in the infertile group was significantly higher by 1.81-fold compared to the control group (p<0.01), whereas, expression of HOXA-10 mRNA was significantly lower in the infertile group compared to the controls (p=0.047)." (PMID 32685419, 2020). "Our data indicates that HOXA10 mRNA expression was 0.69-fold lower in eutopic endometrial tissues of women with infertility compared to those of the control subjects." (PMID 32685419, 2020). "HOXA-10 mRNA expression was lower by 0.69-fold (p=0.047) in the infertile group compared to the controls." (PMID 32685419, 2020). "This study aimed to evaluate the expression of miRNA 135b and HOXA-10 during the implantation window in endometrial tissue of infertile women." (PMID 32685419, 2020). "For example, Homeobox A10 (HOXA-10) transcription levels significantly decreased in infertile patients, when compared to controls." (PMID 28830391, 2017). "Endometrial expression of Hoxa10, which plays a key role in implantation, has been shown to be reduced in ectopic endometrium and as well as in the eutopic endometrium of women with infertility." (PMID 28716123, 2017). "Targeted deletion of the Hoxa10 gene was found to lead to uterine factor infertility in mice, primarily due to failure of embryonic implantation and aberrant decidualization." (PMID 25792996, 2015). "Materials and Methods: Expression of HOXA11 and HOXA10 were examined prospectively during the midluteal phase in endometrium obtained from infertile women (n=12) with myoma before and three months after myomectomy." (PMID 24639724, 2013). "From human and animal studies, hypermethylation of the promoter and surrounding regions of the Hoxa10/HOXA10 may reduce its expression, thereby implicating abnormal methylation in infertility." (PMID 39858500, 2025). "The methylation status of HOXA10 and HOXA11 may serve as a potential diagnostic marker for evaluating and treating infertility." (PMID 41153447, 2025). "Future studies should investigate whether decreased HOXA10 contributes to infertility and uterine disorders." (PMID 40305321, 2025). "Changes in the endometrial expression of the HOXA10 and prokineticin gene family in patients with myoma uteri and endometrial polyps may explain certain aspects of infertility in these patients." (PMID 39915377, 2025). "This review provides similar data on HOXA10 expression in endometriotic women across populations despite different geographical regions, which consequently provides an innovative idea for closing the research gap for infertility treatment." (PMID 37629050, 2023).